TWIST1 (twist family bHLH transcription factor 1)
Diseases named in the same sentence as TWIST1 in open-access papers (continued):
Sharing a sentence is not in itself a finding about the gene and the disease.
osteosarcoma (continued). "However, the mechanistic relationship between miR-580-3p, Twist1 and circRAB3IP in osteosarcoma has yet to be verified." (PMID 34224315, 2021). "Twist1 is a downstream target of HDAC5 in osteosarcoma progression." (PMID 34178647, 2021). "Moreover, circRAB3IP has been revealed to act as the sponge of miR-580-3p to promote TWIST1 expression in osteosarcoma." (PMID 34516354, 2021). "The Twist1 and Wnt/β-catenin signaling pathways play important roles in the development of osteosarcoma, in which Twist1 promotes the expression of specific cell surface receptors in osteosarcoma cells via activating Tcf4-mediated Wnt/β-catenin signaling pathway." (PMID 32974352, 2020). "Previous evidence has indicated that the metastatic procedure in osteosarcoma exhibited EMT like states, exhibited by regulation of EMT-related transcription factors, such as TWIST-1, snail, and Smads, which are involved in the complex invasive and metastatic behavior of osteosarcoma progression." (PMID 31718700, 2019). "Mutations on the coding region of the human TWIST1 gene, leading to haploinsufficiency, have been identified in Saethre–Chotzen syndrome (SCS), in some cases of Baller-Gerold syndrome and in human pediatric osteosarcomas." (PMID 21037858, 2010). "Interestingly, down-regulation, rather than up-regulation of Twist1 is implicated in chemo-resistance in osteosarcoma." (PMID 28099910, 2017). "The TWIST1 negative regulator, deactivated by HDAC5, was not reported, though independently, miR-22 is a known direct regulator of TWIST1 where low miR-22 levels in osteosarcoma tumours contributes to EMT and disease progression through TWIST1." (PMID 40442778, 2025). "For instance, the upregulation of lncRNA AFAP1-AS1 in osteosarcoma (OS) has been showed to promote the tumorigenesis, EMT, and consequent progression of OS cells through the regulation of the RhoC/ROCK1/p38MAPK/Twist1 axis." (PMID 35264071, 2022). "The AFAP1-AS1-mediated increase in Twist1 can enhance expression of N-cadherin and Vimentin, while diminishing E-cadherin levels, thus promoting EMT of osteosarcoma cells." (PMID 34912717, 2021). "Cyclin dependent kinase 5 (CDK5) and Twist Family BHLH Transcription Factor 1 (TWIST1) have been reported to increase metastasis through regulating cell cycle and EMT and they were found to be upregulated in osteosarcoma tumors with low levels of 14q32 miRNAs." (PMID 34066712, 2021). "In MNNG/HOS and U2OS osteosarcoma cells, AFAP1-AS1 has been found to promote tumorigenesis via influencing RhoC/ROCK1/p38MAPK/Twist1 cascade." (PMID 34912717, 2021). "In osteosarcoma, Cyr61 promotes EMT and the metastasis of tumor cells through the Raf-1/MEK/ERK/Elk-1/TWIST-1 signaling pathway." (PMID 34970415, 2021). "AFAP1-AS1 is overexpressed in osteosarcoma and plays an oncogenic role in osteosarcoma through RhoC/ROCK1/p38MAPK/Twist1 signaling pathway, in which RhoC acts as the interaction target of AFAP1-AS1." (PMID 31443665, 2019). "Finally, we used the TWIST-1 short hairpin RNA (shRNA) to demonstrate whether Cyr61-induced cell migration is mediated by TWIST-1 upregulation, and the results revealed that transfection with TWIST-1 shRNA dramatically inhibited Cyr61-induced cell migration in osteosarcoma." (PMID 25326651, 2014). "TWIST1 and TCF4 protein interaction was also validated in osteosarcoma cells." (PMID 33917757, 2021).
bladder cancer (43 papers, 2012 to 2025). "Our findings underscore that TWIST1/Vimentin promoter hypermethylation is significantly associated with the risk of bladder cancer, corroborating several prior studies." (PMID 38575639, 2024). "The overexpression of TWIST1 causes the malignant increase of bladder cancer cells." (PMID 37215997, 2023). "In addition, they showed that TWIST1 was significantly higher in the metastatic lesions compared with the primary site, and the increased TWIST1 expression in bladder cancer was associated with decreased expression of E-cadherin." (PMID 25238494, 2014). "In this study, we utilize a Methylation Assay Kit designed explicitly for the Twist1/Vimentin gene (produced by Jiangsu MicroDiag Biomedicine Co., Ltd., China), intending to assess its diagnostic precision and clinical applicability in patients with bladder cancer." (PMID 38575639, 2024). "In this study, among the 77 bladder cancer patients, the TWIST1/Vimentin positivity was significantly high, reaching 77.9%, whereas, in individuals with other urological malignancies, the positivity rate was only 18.5%." (PMID 38575639, 2024). "Overexpression of TWIST1 or IMPDH1/2 in 5637 cells knockdown UCA1 enhanced migration of bladder cancer cells." (PMID 37215997, 2023). "Exploring the mechanism of TWIST1 participating in guanine nucleotide synthesis in bladder cancer expands the role of TWIST1 in bladder cancer." (PMID 37215997, 2023). "Bladder cancer cells overexpressing UCA1 or TWIST1 had reduced migratory capacity after MPA treatment or knockdown of IMPDH1/2." (PMID 37215997, 2023). "In summary, we have clarified the molecular mechanism by which UCA1 controls IMPDH1/2 expression via TWIST1 to change metabolite levels and promotes guanine nucleotide de novo anabolic reprogramming and bladder cancer progression." (PMID 37215997, 2023). "The upregulation of TWIST1 reversed EMT inhibition by NKX2-8 as well as restored the invasive phenotype of bladder cancer cells." (PMID 37627900, 2023). "PCAF acetylates Twist1 at Lys73, Lys76, and Lys77, which promotes nuclear localization of Twist1 and increases its transcriptional activity in bladder cancer cells." (PMID 33808323, 2021). "CFTR, SAL3, and TWIST1 have been recently shown to be useful for monitoring bladder cancer in a real clinical scenario, as a sensitivity of 96% was achieved by pyrosequencing in combination with urine cytology—however with low specificity (40%)." (PMID 32046186, 2020). "Honokiol reduced steroid receptor coactivator-3 (SRC-3), matrix metalloproteinase (MMP)-2, and Twist1, preventing the invasion of urinary bladder cancer cells." (PMID 31877856, 2019). "Twist1 is significantly upregulated in bladder cancer tissues comparing with normal bladder tissues, and among the cancer tissues, Twist1 was remarkably higher in metastatic lesions comparing with primary tumors." (PMID 30973923, 2019). "Twist1 is co-expressed with P-gp in human bladder cancer cells and knockdown of Twist1 significantly sensitizes bladder cancer cells to anthracycline drugs via inhibiting P-gp expression." (PMID 28099910, 2017). "This DAB2IP/STAT3/Twist1/P-gp axis is crucial for chemo-resistance to the anthracycline drugs (pirarubicin) and tumor re-growth of bladder cancer cells." (PMID 28099910, 2017). "In bladder cancer, Twist1 regulates Y-box-binding protein-1 (YB1) expression and both Twist1 and YB1 are involved in cell growth, invasion, motility, and resistance to cisplatin and doxorubicin, but not to 5-fluorouracil (5-FU)." (PMID 28099910, 2017). "Methylation levels of EOMES, HOXA9, POU4F2, TWIST1, VIM, and ZNF154 in urine specimens are promising diagnostic biomarkers for bladder cancer recurrence surveillance." (PMID 23056278, 2012). "In addition, USP5 stabilizes Twist1 through its deubiquitinase activity, activating the epithelial–mesenchymal transition pathway in bladder cancer." (PMID 40750708, 2025).
bladder cancer (continued). "Furthermore, the long non-coding RNA (lncRNA) UCA1 facilitates bladder cancer progression by recruiting the transcription factor TWIST1 to the promoter regions of IMPDH1 and IMPDH2, thereby upregulating their expression." (PMID 41179679, 2025). "Based on our study, TWIST1 and Vimentin promoter methylation could distinguish bladder cancer patients from healthy/benign subjects with 78% sensitivity and 83% specificity in urine samples." (PMID 38575639, 2024). "Interestingly, a recent study reported that NDRG1 over-expression promoted EMT in bladder cancer through up-regulation of EMT-related transcription factors including Twist1 and Snail2." (PMID 38561462, 2024). "There are few reports on the role of TWIST1 in the metabolism of bladder cancer." (PMID 37215997, 2023). "TWIST1 was already known as a biomarker candidate for the detection of bladder cancer." (PMID 37371512, 2023). "Resveratrol decreased smoke induced EMT in bladder cancer via STAT3/Twist1 inhibition." (PMID 33572742, 2021). "In addition, the NKX2-8/TWIST1 axis plays a crucial role in bladder cancer EMT and may be a potential therapeutic target for bladder cancer." (PMID 37627900, 2023). "For example, one research detects the DNA methylation status of TWIST1, ONECUT2 (2 loci) and OTX1 in urine to diagnose bladder cancer among hematuria patients." (PMID 40855090, 2025). "Bladder cancer patients with tumors that were NKX2-8 positive and low TWIST1 expression had better prognosis as compared to those that were negative NKX2-8 and harbored high TWIST1 expression." (PMID 37627900, 2023). "In urine samples, the methylation status of a urinary biomarker panel (HOXA9, ONECUT2, PCDH17, PENK, TWIST1, VIM, and ZNF154) showed great prediction accuracy in predicting bladder cancer in patients with hematuria." (PMID 37627900, 2023). "miR-203 can target Twist1 to inhibit cell migration and viability, while inhibition of miR-203 and simultaneous interference with Twist1 can promote EMT in bladder cancer cells." (PMID 35805066, 2022). "In another study, the correlation between the methylation levels of EOMES, HOXA9, POU4F2, TWIST1, VIM, and ZNF154 in urine specimens and bladder cancer recurrence surveillance was discovered by real-time PCR." (PMID 33388091, 2021). "Here, we established a combination methylation assay of HOXA9, ONECUT2, PCDH17, PENK, TWIST1, VIM and ZNF154, which had displayed great prediction accuracy of bladder cancer in patients with hematuria by using urine samples." (PMID 31777606, 2019). "In the J82 bladder cancer cell, honokiol repressed the expression of SRC-3, MMP-2, and Twist1 genes which were involved in cancer cell invasion." (PMID 31877856, 2019). "In this study we performed an independent validation of EOMES, HOXA9, POU4F2, TWIST1, VIM, and ZNF154 methylation for the urinary diagnosis in bladder cancer surveillance." (PMID 23056278, 2012). "Hypermethylation of individual biomarkers TWIST1, hTERT, NID2, and VIM was detected with a sensitivity of 92%, 97%, 84%, and 83%, respectively, and a specificity of 100% for each using urine sediment samples in Moroccan bladder cancer patients." (PMID 40141826, 2025). "In bladder cancer tissues, NKX2-8 expression was inversely correlated with TWIST1 expression." (PMID 37627900, 2023). "In addition, a 6-gene panel (HOXA9, EOMES, POU4F2, TWIST1, VIM, and ZNF154) was highly hypermethylated in the urine of bladder cancer patients as compared to healthy individuals." (PMID 37627900, 2023). "In conclusions, a urinary combined methylation assay of HOXA9, ONECUT2, PCDH17, PENK, TWIST1, VIM and ZNF154 displayed accurate prediction of bladder cancer in hematuria patients, which provided the guidance for the patients at early stage tumor and during the follow-up after operation." (PMID 31777606, 2019).
colon carcinoma (42 papers, 2011 to 2025). "In other gastrointestinal cancers such as colon cancer, the stromal expression of TWIST1 has been associated with worse prognosis, even with neoplastic features such as trisomy, and TWIST1 elevated mRNA circulating levels have been detected in the blood of colon cancer patients." (PMID 36497278, 2022). "Our study has revealed that JSD can significantly upregulate E-cad and downregulate N-cad, Vimentin, Snail, Slug and Twist1 in colon cancer cells, leading to a reversion of EMT." (PMID 31772677, 2019). "Our study demonstrated that Twist1 can induce MDR in colon carcinoma by promoting the expression of ABCB1 and ABCC1 in vitro and in vivo." (PMID 28881781, 2017). "Twist1 was overexpressed in the parental HCT-8 cells to verify the role of Twist1 in the MDR of colon carcinoma." (PMID 28881781, 2017). "In summary, our data confirmed that Twist1 plays a vital role in MDR of colon carcinoma by upregulating ABCB1 and ABCC1." (PMID 28881781, 2017). "We also promoted a novel therapeutic strategy to overcome drug resistance through the inactivation of the Twist1 expression in colon cancer." (PMID 28881781, 2017). "Coculturing HT29 human colon carcinoma cells with human platelets led to the induction of mesenchymal-like cancer cells characterized by downregulation of E-cadherin and upregulation of Twist1, enhanced cell mobility and a proaggregatory action on platelets." (PMID 27074574, 2016). "In conclusion, Twist1 induces stem cell-like characteristics by EMT via AKT signaling pathways in colon cancer cell lines, and these pathways depend on the MSI status." (PMID 27494849, 2016). "In conclusion, Twist1 induces stem cell-like characteristics in colon cancer cell lines related to EMT via AKT signaling pathways, and those pathways depend on MSI status." (PMID 27494849, 2016). "By downregulating E-cadherin and upregulating expression of TWIST1, it enhances epithelial-mesenchymal transition and metastasis in colon cancer." (PMID 24564251, 2013). "Moreover, TMEM211-silenced colon cancer cells showed decreased levels of Twist1, N-cadherin, Snail and Slug but increased levels of E-cadherin." (PMID 37367036, 2023). "Furthermore, in colon cancer, the internalized CD44 and acetyltransferase p300 induce STAT3 acetylation at Lysine (Lys) 685, which in turn promotes the expression of cell cycle regulators cyclin D1 70, MYC, and Twist1 in colon cancer cells." (PMID 32754274, 2020). "Thus, Twist1 is a promising therapeutic target against colon cancer in vincristine-based chemotherapy." (PMID 28881781, 2017). "The siRNA-mediated suppression of Twist1 enhanced the drug sensitivity in the colon cancer cells." (PMID 28881781, 2017). "In this study, we examined whether Twist1 induced stem cell-like characteristics by EMT via AKT signaling pathways in colon cancer cell lines and if those pathways depended on MSI status." (PMID 27494849, 2016). "A subsequent study reported that TWIST1 induced EMT and a cancer stem-like cell phenotype, contributing to irinotecan resistance and promoting the migration of colon cancer and invasion." (PMID 36123378, 2022). "In the GCSC database, the methylation levels of FGF8, NOG, TCF15, TWIST1, TBX5, SIX2, and TIAM1 are higher in colon cancer." (PMID 34526059, 2021). "YTHDC2 promotes the metastasis of colon cancer cells by facilitating the translation of hypoxia inducible factor 1 subunit alpha (HIF-1α) and twist family BHLH transcription factor 1 (Twist1) mRNA during hypoxia." (PMID 33928028, 2021). "In this study by using publicly available microarray datasets, we for the first time showed a negative correlation between EVI1 and all the known EMT related transcription factors (SNAIL, SLUG, ZEB1, ZEB2, TWIST1, and TWIST2) in colon cancer patient samples." (PMID 29339729, 2018). "Twist1-mediated promotion of ABCB1 and ABCC1 expression levels plays an important role in the drug resistance of colon cancer cells." (PMID 28881781, 2017).
colon carcinoma (continued). "In this study, we investigated the role of Twist1 and its downstream signaling cascades for inducing EMT in MSS and MSI colon cancer cell lines." (PMID 27494849, 2016). "To investigate Twist1-induced tumorigenesis in vivo according to MSI status, we generated xenografts by implanting MSS LS513 and MSI LoVo colon cancer cells." (PMID 27494849, 2016). "In metastatic colon cancer cells, HMGA1 induces expression of Twist1, a gene involved in embryogenesis, EMT, and tumor progression, while HMGA1 represses E-cadherin, a gene that is down-regulated during EMT and metastatic progression." (PMID 22276142, 2012). "Whereas overexpression of CDK5RAP2 S down-regulated E-cadherin and up-regulated N-cadherin, Vimentin, Zeb1, Slug and Twist1 expression, indicating that CDK5RAP2 L and CDK5RAP2 S might have different roles in EMT of colon cancer cells." (PMID 39048555, 2024). "Genistein reversed the EMT of colon cancer cells by upregulation of E-cadherin and downregulation of N-cadherin, accompanied by the suppression of EMT related makers, such as Snail2/slug, ZEB1, ZEB2, FOXC1, FOXC2 and TWIST1." (PMID 29202800, 2017). "Moreover, markers that induce or indicate EMT in colon cancer were significantly overexpressed in tumors with high CYB5R1 levels, including ZEB1 (r=0.20, p<0.0001), TWIST1 (r=0.22, p<0.0001), and VIM (r=0.29, p<0.0001)." (PMID 27120783, 2016). "Furthermore, in the colon cancer SW480 cells, DNMT3A appears to be recruited by the hypoxia-induced histone mark H3K36me3 to demethylate the HRE in the TWIST1 promoter, thus allowing HIF-1α binding and transcriptional activation of the promoter to initiate the EMT process." (PMID 40764968, 2025). "Our study with mouse colon cancer cell lines also clearly showed that overexpression of SOX2 led to increased expression of mesenchymal markers (vimentin and N-cadherin) and EMT-inducing transcription factors (e.g., TWIST1), supporting its role in promoting EMT in colon cancer." (PMID 40179020, 2025). "The results showed that the high-invasive colon cancer cell line HCT-8 had higher expression levels of Twist1 compared with the low-invasive HT-29 cells and normal colon cell line NCM460 and vincristine treatment upregulated Twist1 expression only in the invasive colon cancer cells." (PMID 28881781, 2017). "Although negative results have been reported between TWIST1 expression and patient survival in colon cancer cases, there are several publications that support this relationship, when analyzing the evolution of patients and mRNA TWIST1 levels in colon cancer and cervix carcinoma." (PMID 21464926, 2011). "Except for the heterozygous deletion of TWIST1 and SNAI1 in CRC, and the lack of SIX2 in colon cancer, all other genes have heterozygous deletions." (PMID 34526059, 2021). "Similarly, suppression of endogenous TMPRSS4 reduced ALDH activity in HT-29 and HCT-116 colon cancer cells, and this was accompanied by downregulation of SLUG, TWIST1, and SOX2, but not BMI1 or CD133." (PMID 34809669, 2021).